CLNK (cytokine dependent hematopoietic cell linker)
Description:
An adapter protein which plays a role in the regulation of immunoreceptor signaling, including PLC-gamma-mediated B-cell antigen receptor (BCR) signaling and FC-epsilon R1-mediated mast cell degranulation (By similarity). Together with FGR, it acts as a negative regulator of natural killer cell-activating receptors and inhibits interferon-gamma production (By similarity). Acts as a positive regulator of both T-cell receptor and natural killer T (NKT) cell receptor signaling in CD4-positive NKT cells (By similarity). Together with MAP4K1, it enhances CD3-triggered activation of T-cells and subsequent IL2 production (By similarity). May be involved in tumor necrosis factor induced cell death by promoting reactive oxidative species generation, and MLKL oligomerization, ultimately leading to necrosis (By similarity). Involved in phosphorylation of LAT (By similarity). May be involved in high affinity immunoglobulin epsilon receptor signaling in mast cells (By similarity).
Synonyms: MIST
Tractability: No criterion of Open Targets' tractability assessment is met for any kind of drug.
Gene: Protein-coding gene on chromosome 4 (10,486,395 to 10,684,768, reverse strand). Ensembl gene ENSG00000109684.
Subcellular location: Cytoplasm
Subcellular location (Human Protein Atlas): Vesicles
Gene Ontology:
Molecular function: protein binding; protein-macromolecule adaptor activity; protein-containing complex binding
Biological process: cell surface receptor protein tyrosine kinase signaling pathway; intracellular signal transduction; mast cell degranulation; negative regulation of natural killer cell activation; positive regulation of natural killer cell cytokine production
Cellular component: cytoplasm; mast cell granule; protein-containing complex
Genetic constraint (gnomAD): Loss-of-function variants: 33 observed, 33.73 expected, observed/expected ratio (o/e) 0.98, 90% interval 0.74 to 1.31. The upper end of that interval is the gene's LOEUF score, 1.31, which puts it in group 5 of 6, group 1 being the genes least tolerant of losing a copy. Missense variants: 350 observed, 347.81 expected, observed/expected ratio (o/e) 1.01, 90% interval 0.92 to 1.1. Synonymous variants: 143 observed, 120.58 expected, observed/expected ratio (o/e) 1.19, 90% interval 1.03 to 1.36.
Homologues: Orthologues: chimpanzee CLNK (98% identical), macaque CLNK (91% identical), pig CLNK (72% identical), dog CLNK (71% identical), rabbit CLNK (66% identical), mouse Clnk (61% identical), rat Clnk (61% identical). Paralogues in human: LCP2 (27% identical), BLNK (18% identical), SH2D6 (16% identical).
Diseases named in the same sentence as CLNK in open-access papers:
CLNK is named in the same sentence as 20 diseases in open-access papers, as found by Europe PMC text mining. Sharing a sentence is not in itself a finding about the gene and the disease. The quoted sentences say what the papers report.
gout (4 papers, 2022 to 2024). A condition characterized by painful swelling of the joints, which is caused by deposition of urate crystals. "A case-control association study of gout in Chinese populations revealed that CLNK SNPs (rs2041215 and rs1686947) are associated with various clinicopathological parameters and might have potential as diagnostic and prognostic markers for patients with gout." (PMID 35813212, 2022). "Existing research suggests that CLNK and WDR1 polymorphisms significantly contribute to gout in certain populations by affecting lipid metabolism." (PMID 39512523, 2024). "Specifically, WDR1 appears to affect gout development via the MAPK signaling pathway, whereas CLNK may operate through the STAT signaling pathway." (PMID 39512523, 2024). "It is hypothesized that CLNK mainly regulates B-cell development and activation and co-mediates the formation of immune complexes through the STAT signaling pathway to promote gout, as suggested be a combination of related studies." (PMID 35813212, 2022).
anemia (1 paper, 2023). A reduction in the number of red blood cells, the amount of hemoglobin, and/or the volume of packed red blood cells. "In summary, this study demonstrated that blood-related indicators such as hemoglobin (α and β), CLNK and GATA may not be activated in RBIV infection and that their immune responses are critical factors for RBIV anemia." (PMID 37984754, 2023).
autoimmune disease (1 paper, 2025). A disorder resulting from loss of function or tissue destruction of an organ or multiple organs, arising from humoral or cellular immune responses of the individual to their own tissue constituents. "SESN3 and CLNK were both associated multiple autoimmune diseases." (PMID 41299435, 2025). "CLNK is involved in immune signaling pathways, and future work will be needed to further disentangle its role in autoimmune disease." (PMID 41299435, 2025). "Interestingly, genetically predicted expression of CLNK in Treg memory cells and B cells had opposite directions of effect on autoimmune disease, including T1D." (PMID 41299435, 2025).
Granuloma (1 paper, 2025). A compact, organized collection of mature mononuclear phagocytes, which may be but is not necessarily accompanied by accessory features such as necrosis. "A diverse array of innate immune cells, including mast cells (MC) (cluster 20: HDC, CPA3, KIT), dendritic cells (DC) (cluster 23: CLNK, WDFY4, FLT3), neutrophils (FCGR3B, FFAR2, CSF3R), and macrophages (CD68, CD163, C1QA/B/C), was also present in these granulomas." (PMID 40772762, 2025).
skin cancer (1 paper, 2023). "Our results show that a marked correlation between the CD103+DC signature (IRF8, FMS‐like tyrosine kinase 3 ligand, CLEC9A, CLNK, XCR1, BATF3, and ZBTB46) and chemokines C‐X‐C motif chemokine ligand 9, CXCL10, and CD8A in a mouse model with DMBA/TPA‐induced skin cancer." (PMID 36891351, 2023).
CLNK also shares sentences with these, for which no sentence is quoted: tumor (2 papers); Alzheimer disease (1); asthma (1); autosomal-recessive intellectual disability (1); cancer (1); cervical cancer (1); Graves disease (1); hypothyroidism (1); infection (1); lung carcinoma (1); myasthenia gravis (1); Obesity (1); primary sclerosing cholangitis (1); resistant hypertension (1); rheumatoid arthritis (1).